BRCA2 (BRCA2 DNA repair associated)
Diseases named in the same sentence as BRCA2 in open-access papers (continued):
Sharing a sentence is not in itself a finding about the gene and the disease.
breast cancer (continued). "About 20% of prostate cancer cases have a familial clustering,BRCA2 mutations in only 5% of PC cases The role of family history in prostate cancer risk appears to be more widespread than previously thought, and there is evidence that prostate and breast cancer can occur together in some patients." (PMID 39364320, 2024). "However, the Breast Cancer Linkage Coalition (BCLC) has previously reported that the relative risk of PC in men with a family of pathogenic BRCA2 mutations is 2.9-4.8, and in certain subgroups, such as those aged 65 years<, the lifetime risk is approximately 20%, with a relative risk of 7.3." (PMID 39364320, 2024). "Finally, an association between breast cancer-related tumor-suppressor genes BRCA1/BRCA2 and RAS may also exist, although the exact mechanism has yet to be established." (PMID 39202050, 2024). "Similarly, the fraction of breast cancers attributable to mutations in BRCA1 or BRCA2 is about 10%." (PMID 36981032, 2023). "Approximately 10% of breast cancer (BC) cases are hereditary, and germline pathogenic variants in BRCA1 and BRCA2 genes account for 20% of familial BC cases." (PMID 38067403, 2023). "Consequently, germline BRCA2 mutations are associated with an increased risk of breast cancer." (PMID 36851449, 2023). "Finally, we applied this BRCA1-specific and the previously published BRCA2-specific models to predict the pathogenicity of variants of uncertain significance that were identified in patients with breast cancer by the Qatari National Center of Cancer Care and Research." (PMID 37335020, 2023). "Furthermore, BRCA2 PTVs were associated with a high risk of breast cancer overall, ER-positive and triple-negative disease and exceeded the 80-year cumulative risk threshold for high risk (30%), as defined by the NICE surveillance screening guidelines ((NICE) 2019)." (PMID 37790698, 2023). "Another meta-analysis included three cohort studies for 1100 healthy women with BRCA1 and BRCA2 P/LP germline variants who underwent risk-reducing bilateral salpingo-oophorectomy before the onset of natural menopause to assess the association between breast cancer incidence and HRT." (PMID 37628558, 2023). "Germline pathogenic variants (PVs) in the tumor suppressor genes BRCA1 (MIM#113705) and BRCA2 (MIM#600185) confer a cumulative lifetime risk of developing breast cancer (BC) by age 80 of 72% and 69%, respectively." (PMID 37168384, 2023). "Thus, the best AUC which could be expected for ovarian cancer predictive tests based on family history and supplemented with information on BRCA1/BRCA2 mutation status is probably similar to that for breast cancer, or about AUC = 0.60–0.65." (PMID 36981032, 2023). "BC risk factors may include a median age at menarche and first pregnancy, menopause at an older age, elevated estradiol levels, stress, Klinefelter syndrome, obesity, coffee intake, radiation exposure, gynecomastia, a family history of breast cancer, as well as BRCA2 and BRCA1 mutations." (PMID 37079213, 2023). "It has been largely demonstrated that pathogenic mutations in the BRCA1 and BRCA2 genes increase the risk of developing breast cancer, respectively, by 65% and 45%, and are responsible for 90% of all hereditary BC cases." (PMID 37111307, 2023). "Similar trends were observed for unaffected women, where BRCA1 (OR 2.34, 95% CI 2.13, 2.56) and BRCA2 (OR 1.25, 95% CI 1.16, 1.35), were associated with a significant increase in risk among women with a relative diagnosed ≤ 45 versus > 45 years of age with breast cancer." (PMID 37084156, 2023). "However, they concluded that there is currently insufficient evidence to propose individualized recommendations for dietary habits or weight management specifically for women with BRCA1 and BRCA2 germline variants compared to the general population regarding breast cancer risk reduction." (PMID 37628558, 2023).
breast cancer (continued). "However, to high breast cancer risk associated with alterations in BRCA1 or BRCA2, both studies confirmed association of germline pathogenic CHEK2 variants with moderate breast cancer risk with odds ratio (OR) 2.5 and a cumulative lifetime breast cancer risk of 25%–30%." (PMID 37449874, 2023). "Therefore our aim was to develop a BRCA1-specific machine learning model to predict the pathogenicity of all types of BRCA1 variants and to apply this model and our previous BRCA2-specific model to assess BRCA variants of uncertain significance (VUS) among Qatari patients with breast cancer." (PMID 37335020, 2023). "Besides the relatively well-documented hereditary cases explained partly by BRCA1 and BRCA2 gene mutations, alterations of several other genes have been identified as susceptibility factors for breast carcinoma, but a significant fraction of the heritability of the disease is still unexplained." (PMID 37239898, 2023). "Indeed, up to 80% of BRCA2 mutations occur in patients with ER+/HER2- breast cancers." (PMID 35158866, 2022). "Additionally, oncoprint analysis showed that BRCA1 and BRCA2 mutations, whether germline or somatic, were mutually exclusive in ovarian cancer and breast cancer." (PMID 34979999, 2022). "BRCA1 and BRCA2 germline mutations are associated with an aggressive BC course (the triple-negative breast cancer subtype especially) and advanced OC." (PMID 35409996, 2022). "Pathogenic variants in BRCA1 and BRCA2 genes account for approximately 50% of all hereditary BC, with 60-80% of patients characterized by Triple Negative Breast Cancer (TNBC) at an early stage phenotype." (PMID 36741700, 2022). "Male breast cancer (mBC) is associated with a high prevalence of pathogenic variants (PVs) in the BRCA2 gene; however, data regarding other BC predisposition genes are limited." (PMID 35805063, 2022). "Between genetic risk factors, mutations to the breast cancer gene (BRCA) (BRCA1 and BRCA2) are thought to be able to give approximately from 5% to 10% of all BC." (PMID 36412681, 2022). "Women with a pathogenic germline mutation in the BRCA1 or BRCA2 gene face a high risk of developing breast cancer (BC) and ovarian cancer (OC)." (PMID 35172875, 2022). "The women carriers of pathogenic variants (mutations) in the BRCA1 and BRCA2 genes (BRCA1/2) show a very high risk of breast cancer (BC) and/or ovarian cancer (OC)." (PMID 35356420, 2022). "Interestingly, RRBM-RRBSO or only RRBSO was the most effective prevention strategy in patients with luminal breast cancer aged over 35 years with the BRCA2 pathogenic variant in exons 12-25 in stage II and in patients aged over 49 years with the BRCA2 pathogenic variant in exons 1-10 in stage II." (PMID 36580360, 2022). "In addition, BRCA2-N372H is a variant associated with breast cancer and epithelial ovarian cancer." (PMID 34367235, 2021). "However, it has been previously reported that the frequency of PIK3CA mutations may be different in breast cancer patients based on the presence of germline mutations in BRCA1/BRCA2 (in both women and men)." (PMID 34287479, 2021). "In addition, MMG has been reported to show calcification only in BRCA2-associated breast cancer." (PMID 34674065, 2021). "Thus, since the Amerindians were one of the forming group of the Latin Americans, they have similarities in their genomic profile, including the BRCA1 and BRCA2 genes, a fact that can be extremely relevant in the likely high frequency of variants linked to breast cancer in these populations." (PMID 33499154, 2021). "Interestingly, genotype-phenotype analyses of BRCA2 breast cancer pedigrees mirror the observations in biallelic BRCA2 mutation cases, with different cancer risks associated with monoallelic truncating mutations in exon 11 when compared with mutations located in 3′ or 5′ of this exon." (PMID 34456966, 2021).
breast cancer (continued). "The most frequent predisposing genetic alterations are in the BRCA1 and BRCA2 genes, with a cumulative lifetime risk for breast cancer (BC) of 72% and 69% for carriers of pathogenic variants in BRCA1 and BRCA2, respectively." (PMID 34503502, 2021). "However, high-risk genes such as BRCA1 and BRCA2 account for less than 15% of breast cancer cases, which suggests that numerous breast cancer-related risk genes have not been discovered, and these gene polymorphisms influence susceptibility to breast cancer." (PMID 33632172, 2021). "Indeed, more than 44.44% of carriers harbor BRCA1-c.211dupA or BRCA2-1310_1313deAAGA mutations which highlights the importance of screening these mutations in the treatment workflow of cases with early onset or strong family history of breast cancer." (PMID 34490083, 2021). "Observational studies have shown that BRCA1 mutation carriers giving birth at aged 30 years or older might have a lower risk of breast cancer, with a higher risk of breast cancer of a BRCA2 mutation carrier's first pregnancy happening before the age of 30 serving as a contrast." (PMID 34376160, 2021). "Thus, the BRCA2-associated risk could be higher for pancreatic than for breast cancer, as indicated by our analysis of pooled patients against gnomAD data (BRCA1: OR = 6.0 vs. BRCA2: OR = 11.7)." (PMID 34503238, 2021). "For instance, genomic alternations such as specific mutations in breast cancer 1 (BRCA1) and breast cancer 2 (BRCA2) genes are well-established tumor biomarkers used for breast cancer risk assessment, meaning that women bearing these mutations are predisposed to develop breast cancer." (PMID 34439360, 2021). "The observed associations between ER status, survival and exposure to ovarian hormones may relate to the tissue specificity of cancers in BRCA2 mutation carriers; mutation carriers have dramatic increases in susceptibility to both female breast and ovarian cancer, and breast cancer in males." (PMID 32939053, 2020). "BRCA1 and BRCA2 are cancer predisposition genes that are inactivated in ~25% of inherited breast cancers, ~15% of all ovarian cancers and several other cancers, suggesting that PARP inhibitors might have potential in treating a wide-range of patients with BRCA-deficient tumours." (PMID 32183301, 2020). "PARP1 was proposed as a new treatment for cancer, as the synthetic lethality concept suggested that its depletion in breast-cancer patients with germline mutations in the BRCA1 or BRCA2 genes, key molecules in the homologous recombination (HR) pathway, could cause cancer cell death." (PMID 32046300, 2020). "BRCA1 and BRCA2 (breast cancer predisposition gene 1/2)are the strongest susceptibility genes for BCaccounting for up to half of the heritable mutations in BC and inherited in an autosomal dominant pattern with incomplete penetrance." (PMID 32102521, 2020). "Additionally, nonsense mutations found in Chilean breast cancer families may interfere with normal BRCA2 function." (PMID 32356124, 2020). "Breast cancer incidence peaks or plateaus at a younger age (early 40s) in BRCA1 than BRCA2 mutation carriers, perhaps suggesting that much of the carcinogenic process in BRCA1 mutation carriers takes place before women typically have RRSO and could influence disease incidence." (PMID 31948486, 2020). "Our recent observation that HsRAD52-S346X protects against breast cancer in carriers of pathogenic BRCA2 mutations suggests the possibility that a similar loss of HsRAD52-dependent HRR in human cells may contribute to the synthetic lethality that underlies this protection." (PMID 33015141, 2020). "Among inherited mutations, BRCA1 e BRCA2 (BReast CAncer) suppressor genes are the most involved in BC susceptibility." (PMID 32722276, 2020).
breast cancer (continued). "Previous population studies have identified several BRCA1/2 pathogenic mutations in Caucasians, for example, BRCA1 c.68_69del, BRCA1 c.5266dup, and BRCA2 c.5946del were the most frequent variants and could greatly increase the cumulative risk of breast cancer during a woman's lifetime." (PMID 32879886, 2020). "Studies have estimated that the penetrance of BRCA1 and BRCA2 gene mutations are association with the incidence of breast cancer only in 6%–8% of all breast cancer cases, and the cumulative incidence of sporadic breast cancer in approximately 90%–95% of the general population." (PMID 33180852, 2020). "Besides BRCA1 and BRCA2, more than 100 loci are known to be associated with breast cancer risk." (PMID 33240314, 2020). "However, the majority of hereditary breast and ovarian cancers (HBOC) are due to highly penetrant germline BRCA variants, which are inherited in an autosomal-dominant fashion: breast cancer susceptibility gene 1 (BRCA1) or breast cancer susceptibility gene 2 (BRCA2)." (PMID 32806537, 2020). "Women who have inherited pathogenic variants (mutations) in the BRCA1 and BRCA2 genes (BRCA1/2) face a very high lifetime risk of developing breast cancer (BC) and/or ovarian cancer (OC)." (PMID 33266155, 2020). "In addition, researchers reported that approximately 40% of women with pathogenic BRCA1 mutation and approximately 26% of women with pathogenic BRCA2 mutation develop secondary breast cancer in the contralateral 20 years after the first diagnosis of breast cancer." (PMID 33488844, 2020). "Regarding PALB2 (Partner And Localizer of Breast Cancer Type 2 susceptibility protein (BRCA2)), mutations in this gene have been associated with increased risk of BC." (PMID 31817194, 2019). "Likewise, the prevalence of BRCA2 mutations among breast cancer patients was 17% (95% CI: 9–27%)." (PMID 30898109, 2019). "Therefore, for BRCA2 mutation carriers BC surveillance may be as effective as BRRM regarding breast cancer-specific survival." (PMID 31302855, 2019). "Mutations in the BRCA1 and BRCA2 genes represent a predisposing factor for breast cancer, similarly to a family history of breast cancer or personal history of neoplastic diseases or breast cancer Finally, dense breast is an independent risk factor of breast cancer." (PMID 30934972, 2019). "Moreover, mutations in BRCA1 and BRCA2 genes affect both hereditary and sporadic breast cancers." (PMID 30909550, 2019). "Thus, the goal of this study was to prospectively evaluate whether plasma RANKL levels are associated with the risk of breast cancer among women with a BRCA1 or BRCA2 mutation." (PMID 31069010, 2019). "However, diploidy has been correlated to worse prognosis in BRCA2-associated human breast cancers." (PMID 30930946, 2019). "This may be due to the fact that testing for BRCA2/BRCA1 mutations is perceived as more informative for prevention than determining treatment options in breast cancer, although recent research on the BRCA1/BRCA2 mutation carriers’ response to carboplatin therapy suggest this perception may change." (PMID 30689103, 2019). "Similarly, the G allele of rs2910164, located within miR146a which may bind to the 3′ untranslated regions of the BRCA1 and BRCA2 genes and thus regulate their expression, has been associated with breast cancer risk (OR=1.77; 95% CI=1.40-2.23)." (PMID 31379942, 2019). "Somatic mutations in BRCA1 and BRCA2 mutations may also arise in sporadic cases of breast cancer." (PMID 31022191, 2019). "Therefore, we hypothesized that the difference in immunophenotype between BRCA1- and BRCA2-deficient breast cancers may be attributed to PTEN loss, such as that mediated by inactivating PTEN gene mutations." (PMID 31022191, 2019). "The increased sensitivity of TN breast cancer cells to olaparid in presence of NAMPT inhibitor could be due most probably to the defect in homologous recombination genes (such as loss-of-function BRCA1 or BRCA2 mutations)." (PMID 31803365, 2019).
breast cancer (continued). "Interestingly, the proportion of PALB2-associated breast cancers displaying mono-allelic PALB2 inactivation was comparable to the one of BRCA1-associated and BRCA2-associated breast cancers from TCGA harboring BRCA1 or BRCA2 mono-allelic inactivation, respectively." (PMID 31428676, 2019). "Therefore, it is conceivable that PTEN loss, such as that mediated by inactivating PTEN gene mutation, may be one mechanism underlying the differences in immunophenotype between BRCA1- and BRCA2-deficient breast cancers." (PMID 31022191, 2019). "However, BRCA2-associated breast cancer may be associated with poorer survival compared to sporadic breast cancer." (PMID 30174725, 2018). "The BRCA2 rare nonsense variant (rs11571833) has previously been associated with moderately (OR ranging between 1.26–6.0) increased susceptibility to lung, pancreatic, esophageal and breast cancer was also reported to be significantly over-represented in melanoma patients (OR = 2.80, p = 0.035)." (PMID 30286154, 2018). "Given that BRCA1 and BRCA2 were identified more than 20 years ago, preventive mastectomy remains the gold standard, and mutation carriers have strong preferences for chemoprevention, it is timely that an effective breast cancer risk reduction option be identified." (PMID 30572612, 2018). "For the woman with an inherited BRCA1 or BRCA2 mutation who wishes to do everything possible to avoid developing breast cancer, risk-reducing mastectomy at age 25 is undoubtedly the optimal strategy; however, for many mutation carriers, other factors may be of equal or greater importance." (PMID 30513626, 2018). "Thus, the role of BRCA1 and BRCA2 mutations in the pathogenesis of breast cancer led us to hypothesize that patients with these mutations might have a worse prognosis than non-carriers." (PMID 29152070, 2017). "However, after subgroup analysis by study design stratification, we found that the BRCA2 rs144848 N372H polymorphism was associated with increasing the risk of breast cancer in population-based studies (H allele vs. N allele, OR = 1.034, 95% CI = 1.000-1.068, p = 0.047)." (PMID 28418854, 2017). "A female participant who was carrying a BRCA2 gene mutation and had higher risk of ovarian and breast cancer put a high value on diet and exercise, both for herself and her family, although she implied that she did not expect that this could in any way cancel out or reduce her elevated genetic risk." (PMID 27312973, 2017). "By age 80 years, male carriers of BRCA2 mutations are predicted to have a risk of prostate cancer that ranges from 19% for those at the bottom 5% of the risk distribution to 61% for those at the top 5% of the distribution, and a breast cancer risk that ranges from 5% to 14%." (PMID 28448241, 2017). "BRCA1 and BRCA2, the first gene mutations associated with a predisposition for a high risk of breast cancer, confer an estimated risk of 65 and 45% for BC and 39 and 10% for OC, respectively." (PMID 27779110, 2017). "Therefore, the overall PRS from the general population, which is associated primarily with ER-positive breast cancers, may be more predictive of breast cancer in BRCA2 mutation carriers at younger ages." (PMID 28376175, 2017). "However, the expression of these up-regulated ones were decreased once pyrvinium pamoate was added, among which several (breast cancer susceptibility gene (BRCA2), DNA ligase IV (LIG4) as well as recombinase RAD51) exhibited significantly decreased P-values as compared with doxorubicin alone group." (PMID 27303922, 2016). "Hence, we could expect an overall frequency of about 14.3% of BRCA2 germline mutations in Portuguese male breast cancer patients in an unselected hospital-based cohort." (PMID 27532258, 2016). "Besides BRCA1 (and BRCA2) mutation carriers, also other women with increased risk of breast cancer could benefit from such a prevention strategy." (PMID 27881737, 2016).